TBC1D3H (TBC1 domain family member 3H)
Description:
Acts as a GTPase activating protein for RAB5. Does not act on RAB4 or RAB11 (By similarity).
Tractability: Antibody: UniProt places it where antibodies can reach, with medium confidence; its Gene Ontology location is reachable by antibodies, with medium confidence. PROTAC: UniProt records ubiquitination sites on it.
Gene: Protein-coding gene on chromosome 17 (36,377,531 to 36,388,435, reverse strand). Ensembl gene ENSG00000274226.
Subcellular location: Cell membrane
Subcellular location (Human Protein Atlas): Vesicles
Gene Ontology:
Molecular function: GTPase activator activity
Cellular component: endosome; membrane; plasma membrane
Homologues: Orthologues: chimpanzee TBC1D3B (96% identical). Paralogues in human: TBC1D3G (99% identical), TBC1D3D (99% identical), TBC1D3 (99% identical), TBC1D3B (99% identical), TBC1D3C (99% identical), TBC1D3I (99% identical), TBC1D3L (99% identical), TBC1D3E (99% identical), TBC1D3F (99% identical), TBC1D3K (99% identical), TBC1D26 (30% identical), USP6NL (29% identical), and 33 more.
Diseases named in the same sentence as TBC1D3H in open-access papers:
TBC1D3H is named in the same sentence as 1 disease in open-access papers, as found by Europe PMC text mining. Sharing a sentence is not in itself a finding about the gene and the disease. The quoted sentences say what the papers report.
cancer (1 paper, 2022). A tumor composed of atypical neoplastic, often pleomorphic cells that invade other tissues. "Moreover, the top three unstable methylation genes, TBC1D3H, CSMD1, and ROBO2, were all related to cancer." (PMID 35321246, 2022).